IL17A (interleukin 17A)
Diseases named in the same sentence as IL17A in open-access papers (continued):
Sharing a sentence is not in itself a finding about the gene and the disease.
acute kidney injury (32 papers, 2015 to 2025). Sudden and sustained deterioration of the kidney function characterized by decreased glomerular filtration rate, increased serum creatinine or oliguria. "Interleukin-17A is a key inflammatory factor that contributes to the occurrence and development of several pathogenic injuries such as severe intestinal injury, pancreatic injury, and acute kidney injury." (PMID 35221923, 2022). "Acute kidney injury is characterized by a high inflammatory state, reduced cytokine clearance, and elevated levels of systemic cytokines, such as interleukin (IL)-17A, IL-6, IL-8, IL-1β, IL-12, and tumor necrosis factor (TNF)-α, which aggravate lung injury and increase the risk of lung infection." (PMID 39724279, 2024). "Compared with patients without IL-17A expression, patients with IL-17A expression have higher Scr, increased proteinuria, and more severe tubulointerstitial damage, which are strongly associated with progression to renal failure." (PMID 33717080, 2021). "IL-17A levels were similar in patients with and without HE (87.3 ± 264.7 vs. 100.3 ± 243.3 pg/mL; p = 0.835), ascites (96.4 ± 241.2 vs. 101.4 ± 250.3 pg/mL; p = 0.917), and renal failure (120.4 ± 251.6 vs. 93.3 ± 244.7 pg/mL; p = 0.523)." (PMID 41200179, 2025).
bacteremia (32 papers, 2010 to 2025). "Whereas the blocking of IL-17A was associated with reduced levels of bacteremia, proinflammatory cytokines and an increased survival rates of animals." (PMID 25614712, 2014). "Decreased levels of IL-17A are correlated with increased risk of bacteremia." (PMID 32849528, 2020). "When IL-18 was given to septic mice to mimic the human condition, mortality was dramatically increased compared to septic mice alone and was associated with increased bacteremia, intestinal injury, and an increased systemic inflammatory response predominated by IL-17A." (PMID 28224121, 2017). "Our results demonstrate circulating IL-17A as the most influential cytokine in predicting mortality from APMB and support these findings, suggesting subversion of IL-17A in host response to bacteremia by persistent MRSA isolates." (PMID 39966757, 2025). "The present data showed IL-17A and IL-6 were significantly increased in candidemia patients compared to both bacteremia patients and normal healthy controls." (PMID 34684298, 2021). "Regarding time interval (−1; 2), patients with IC (other) had significantly lower IL-17A levels than patients with E. coli bacteremia (p < 0.001)." (PMID 33535593, 2021). "In a study that reported IL-17A as the most predictive marker for persistent bacteremia, baseline levels were also noted to be highest in patients with an endovascular source." (PMID 33820537, 2021). "Activated neutrophils are the major inflammatory cells that express IL-17A, which can be used as a predictor of S. aureus bacteremia." (PMID 33588861, 2021). "Likely, anti-IL-17A antibody reduces systemic levels of proinflammatory cytokines/chemokines and bacteremia, improving the survival rate." (PMID 32849528, 2020). "In septic animal models, a neutralizing antibody against IL-17A exerted protective effects by reducing bacteremia, lung injury, and abscess formation." (PMID 31531179, 2019). "For example, IFN-γ and IL-17A are involved in efficacious vaccine responses in mouse models of MRSA bacteremia and SSSI due to S. aureus, and these same immune response profiles are observed in humans immunized with this vaccine candidate." (PMID 25309545, 2014). "However, in the context of bacteremia, recent work has found that elevated IL-17A is correlated with APMB and mortality, especially when paired with IL-10 levels." (PMID 39966757, 2025). "These mice are extremely susceptible to a sublethal infection by S. pneumoniae and develop fatal bacteremia, probably related to massive neutrophil recruitment in the lung associated with the lack of IL-17A increase." (PMID 30333823, 2018). "Further, NDV-3 protection against MRSA bacteremia was abrogated in IL-17A null mice." (PMID 25309545, 2014). "Early response cytokines (i.e. first wave at initiation of bacteremia) included IFN-γ, IL-1β, IL-6, IL-18, IL-1ra, IL-10, IL-12 (p40), IL-17a and MCP-1, which all reached peak levels during bacteremia." (PMID 35925895, 2022). "Cytokines and chemokines, including IL-6, IL-10, IL-17A, and MIP-2 were induced systemically and in the lungs of rats with S. aureus bacteremia." (PMID 25978669, 2015). "Using a definition of ≥4 days, our current study identified IL-10 and TNF quartiles, but not IL-17A, measured on Day 1 to be the most predictive for persistent bacteremia." (PMID 33820537, 2021). "An increase in IL-6 and IL-10, but not in IFN-γ or IL-17A, was observed in two of three piglets with pronounced bacteremia 16 to 20 h after infection, but not in piglets with controlled bacteremia." (PMID 31947746, 2020). "When SAcfDNA was combined with IL-17A, the analyte previously reported as the sole biomarker prognostic power for distinguishing persistent bacteremia cases in this cohort, it did not improve the prognostic value of IL-17A by AUROC or in a logistic regression model." (PMID 31041341, 2019). "Thus, IL-17A may be more important in the control of S. aureus infections in the tissue rather than protection once bacteremia has occurred." (PMID 37483624, 2023).
bacteremia (continued). "Using a mouse model of S. aureus bacteremia, we demonstrated that IL-17A/F and TNF-α had no significant impact on survival, whereas IL-1R signaling was critical for survival during S. aureus bacteremia." (PMID 37483624, 2023). "However, since IL-17A/F cytokines were not important for host survival herein, and γδ T cells produce IL-17 cytokines in response to IL-1R signaling, it begs the question of how γδ T cell-intrinsic IL-1R signaling is mediating protection against S. aureus bacteremia?" (PMID 37483624, 2023). "Taken together, we uncovered a role for IL-1R, but not IL-17A/F and TNF-α in protection against S. aureus bacteremia." (PMID 37483624, 2023).
Behçet’s disease (32 papers, 2010 to 2026). "In the differential diagnosis of vulvar ulcers, it is crucial to consider paradoxical reactions such as Behçet’s disease induced by IL-17A inhibitors." (PMID 41010307, 2025).
Erythema (32 papers, 2014 to 2026). Redness of the skin, caused by hyperemia of the capillaries in the lower layers of the skin. "Myr treatment significantly alleviated IMQ-induced erythema, scaling, and epidermal thickening, improved skin-barrier function, and reduced the expression of IL-6, IL-17A, and TNF-α." (PMID 41471291, 2025). "The M7 anti-IL-17A aptamer-treated group findings demonstrated a significant decrease in erythema, scaling, thickening, and PASI score versus the IMQ group (P < 0.05)." (PMID 39045230, 2024). "The IL-17A inhibitor secukinumab induced a significant reduction in erythema and scaliness and a resolution of ectropion in a patient with ABCA12-associated ARCI." (PMID 36980989, 2023). "However, IL-17A treated STAT3 mice dorsal skin showed erythema and flaky scaling." (PMID 37465147, 2023).
helminth infection (32 papers, 2008 to 2026). "Taken together, our results reveal an IL-17A-neutrophil-axis that can drive IL-33 during helminth infection, highlighting an additional pathway by which IL-17A regulates pulmonary type 2 immunity." (PMID 37783278, 2023). "Along the same line, blocking IL-10R or neutralizing IL-10 restores Th1 (IFN-γ, TNF-α) and Th17 (IL-17A, IL-17F) responses and ameliorates Mtb control that is blunted, respectively, by influenza A and helminth infection." (PMID 35113966, 2022). "In our effort to understand how IL-17A might be required for full type-2 immunity, we have discovered that IL-17A suppresses early IFNγ expression in the lung during helminth infection." (PMID 32636457, 2020). "We found that natural helminth infection with S. mansoni but not Ascaris exhibited an increased IL-17A response." (PMID 35976976, 2022). "Overall, these data demonstrated a significant impairment of the type-2 response in the absence of IL-17A during helminth infection, with lung CD4+ T cells failing to become fully activated and produce type-2 cytokines." (PMID 32636457, 2020). "The cytokine profile also confirmed that rTsPmy-pulsed DCs stimulated T. spiralis-infected mouse CD4+ cells to secrete IL-4, IL-10, TGF-β and IL-17A, but not IFN-γ, consistent with the Th2-skewed immune response induced by helminth infections." (PMID 27809931, 2016).
liver cancer (32 papers, 2012 to 2025). An epithelial or non-epithelial malignant neoplasm that arises from the liver. "Liver cancer is closely associated with immune responses that involve IL-17A, which is highly expressed in hepatocytes." (PMID 39906741, 2024). "IL-17A is implicated in the development of chronic inflammatory diseases in the brain, skin, and liver as well as liver cancer." (PMID 33292701, 2020). "At present, IL-17A has been used to study hepatitis, liver transplantation, liver cancer, cholangitis, and other liver diseases." (PMID 39906741, 2024). "This modulation decreases IL-10, TGF-β, and IL-17A levels in the serum of liver cancer mice (p < 0.01), while increasing IL-2 and IFN-γ levels (p < 0.01)." (PMID 39274982, 2024). "The CXCR2 axis has been reported to induce angiogenesis in liver cancer mouse models via IL-17A." (PMID 41155662, 2025). "Notably, IL-17A promotes CXCR2-dependent angiogenesis in liver cancer." (PMID 36980564, 2023). "To date, many studies have focused on the direct interaction between IL-17a and tumor cells, but there is no clear evidence showing that IL-17a can promote the growth, invasion, and metastasis of liver cancer cells by acting on HSCs." (PMID 38740736, 2024).
synovitis (32 papers, 2005 to 2025). Inflammation of a synovial membrane. "Synovitis and articular cartilage loss was also inhibited by IL-17A/F-deficiency in hIL-1α cTg mice." (PMID 30361689, 2018). "Studies have shown that IL-17A and IL-17F have significant expression in lesional psoriatic skin and in cases of synovitis." (PMID 34945224, 2021). "VEGF is produced by monocytes, macrophages and fibroblasts; and together with IL-17A stimulates angiogenesis leading to cell recruitment and synovitis development." (PMID 28173831, 2017). "Several immunopathological studies of human synovitis indeed reported a pronounced IL-17A staining of mast cells and, to a lesser degree, neutrophils while IL-17A-positive T cell were virtually undetectable." (PMID 26156866, 2015). "Although the reduction of the burden of synovitis seems to be crucial for achieving protection from bone erosion, it is not fully clear whether these targets are indeed achieved by IL-17A inhibition." (PMID 30053825, 2018). "Collectively, our data suggest that activation of a CD31-driven, αβTCR-independent, IL-17A-mediated T cell-FLC inflammatory circuit drives and/or perpetuates synovitis." (PMID 30127787, 2018). "Link between IL-17, myelopoeiesis and neutrophils.IL-17A induces PsO like skin lesions.IL-17 can induce bone erosions in absence of synovitis." (PMID 34485340, 2021).
cystic fibrosis (31 papers, 2010 to 2025). Autosomal recessive disorder caused by pathogenic variants in the CFTR gene (cystic fibrosis transmembrane conductance regulator), which encodes a chloride and bicarbonate channel expressed in epithelial cells, and follow the diagnosis criteria. "Our observations are in concert with reported reduced levels of IL-17A upon treatment with exogenous pentraxin-3 in murine models of chronic P. aeruginosa lung infection and cystic fibrosis and suggest an inverse correlation between pentraxin-3 and IL-17A dependent pathway." (PMID 35387000, 2021). "Our previous work unveiled a positive and a negative correlation between levels of gamma interferon (IFN-γ) and interleukin-17A (IL-17A), respectively, and lung function in cystic fibrosis, particularly in patients chronically infected with Pseudomonas aeruginosa." (PMID 30455194, 2019). "First, we found that IL-17A levels were sustained in mice at both early and advanced stages of P. aeruginosa chronic infection and confirmed these observations in human respiratory samples from cystic fibrosis patients infected by P. aeruginosa." (PMID 27189736, 2016). "Notably, ThIL-17 cells, the main producers of IL-17A, are found in airways submucosa early in the course of cystic fibrosis, and IL-17A levels are increased in sputum during pulmonary exacerbations of CF and return to normal only after treatment." (PMID 25141009, 2014). "Human neutrophils from cystic fibrosis patients were also shown to produce IL-17A." (PMID 23401702, 2013). "The role of the IL-17A/IL-23 axis and Th17 cells in cystic fibrosis remains unclear." (PMID 21143945, 2010). "Our previous results showed that in cystic fibrosis patients, gamma interferon (IFN-γ) production by circulating immune cells positively correlated with lung function, while a negative correlation was found in the case of interleukin-17A (IL-17A)." (PMID 30455194, 2019). "Concerning other TLRs, Mizunoe and colleagues reported that IL-17A enhanced the production of IL-8 induced by peptidoglycan (TLR2 agonist) or lipopolysaccharide (TLR4 agonist) in bronchial epithelial cells from cystic fibrosis patients, but not in NHBE cells." (PMID 26418032, 2015). "In addition, IL-17A also synergizes with TLR2 and TLR4 ligands to increase IL-8 production in a human cystic fibrosis bronchial epithelial cell lines." (PMID 23956759, 2013).
gout (31 papers, 2012 to 2025). A condition characterized by painful swelling of the joints, which is caused by deposition of urate crystals. "The present study evaluated the association between IL-17A rs2275913, IL-17F rs763780, and IL-17RA rs4819554 single nucleotide polymorphisms (SNPs) as well as serum concentrations of IL-17A and IL-17F with gout susceptibility in a male Chinese Han population." (PMID 26890073, 2016). "The H&E staining revealed that miR-23a-5p mimic treatment alleviated gout symptoms, whereas IL-17A treatment exacerbated these symptoms." (PMID 41578764, 2025). "Both in vivo and in vitro, miR-23a-5p expression was downregulated, whereas IL-17A expression was upregulated in the gout models." (PMID 41578764, 2025). "The plasma concentrations of IL-17A and IL-17F were measured in 228 gout patients and 198 controls that came from above samples by an enzyme-linked immunosorbent assay." (PMID 26890073, 2016). "In SF, CXCL10 and IL-17A mRNA and protein levels are higher in patients with PsA than in those with OA or gout and similar to those of patients with RA." (PMID 27964744, 2016). "In addition, miR-23a expression in the ankle joints of rats was verified using qPCR; miR-23a mRNA was upregulated by the miR-23a mimic in rats with gout, whereas IL-17A was downregulated." (PMID 41578764, 2025). "IL-17A was also more elevated in our analysis of flaring versus inter-critical gout." (PMID 37810213, 2023). "Dapansutrile may reduce the expression of MMP3 by regulating IL6, IL18, and IL17A, thereby degrading the extracellular matrix to deal with gouty arthritis." (PMID 36105284, 2022). "Dapansutrile may regulate extracellular matrix degradation by reducing MMP3 expression through IL6, IL18, and IL17A in the treatment of gouty arthritis." (PMID 36105284, 2022). "We speculate that IL-17A and IL-17F together play a role in gout pathogenesis, which needs further investigation." (PMID 26890073, 2016). "Levels of serum IL-17A and IL-17F were significantly decreased in gout patients (both p<0.001)." (PMID 26890073, 2016). "IL-17A was found to be 37.5-fold greater (p = 1.5 × 10−5) in patients with PsA than in those with OA and 19.8-fold greater (p = 1.7 × 10−4) than in patients with gout." (PMID 27964744, 2016). "Finally, dapansutrile may reduce the expression of MMP3 by regulating IL6, IL18, and IL17A, thereby degrading the extracellular matrix to treat gouty arthritis." (PMID 36105284, 2022). "Therefore, Dapansutrile may decrease the expression of MMP3 by regulating IL6, IL18, and IL17A, thereby degrading the extracellular matrix for the treatment of gouty arthritis." (PMID 36105284, 2022). "Indeed, similar to what we saw in CXCL10 and CXCR3 levels, we observed that mRNA expression and protein levels of IL-17A were comparable between PsA and RA samples, in accordance with reports in the literature, and significantly higher than in OA and gout SF samples." (PMID 27964744, 2016). "By directly targeting IL-17A, miR-23a-5p plays a pivotal role in regulating NLRP3 inflammasome activation both in THP-1 cells and gout rats." (PMID 41578764, 2025). "The same trend was observed for IL-17A, where levels in PsA SF (median 7.77 pg/ml, IQR 3.26–18.14 pg/ml) were higher than both OA SF (median 3.20 pg/ml, IQR 1.55–3.20 pg/ml; p = 9.3 × 10−4) and gout SF (median 3.20 pg/ml, IQR 2.35–6.40 pg/ml; p = 0.027)." (PMID 27964744, 2016). "CXCL10, IL-17A, and TBX21 expression were elevated in SF cells of patients with PsA compared with those of patients with OA and gout, but not those of patients with RA." (PMID 27964744, 2016).